MIR7111 (microRNA 7111)
Synonyms: hsa-mir-7111
Gene: MicroRNA gene on chromosome 6 (35,470,508 to 35,470,579, forward strand). Ensembl gene ENSG00000276712.
Homologues: Orthologues: chimpanzee MIR7111 (100% identical).